YAP1 (Yes1 associated transcriptional regulator)
Diseases named in the same sentence as YAP1 in open-access papers (continued):
Sharing a sentence is not in itself a finding about the gene and the disease.
cancer (continued). "By inhibiting YAP1 in vitro and performing a meta-analysis of cancer patient cohorts, we confirmed the role of YAP1 in the tumorigenesis of MSCs." (PMID 35356283, 2022). "While attenuating cell growth, TAZ depletion conferred cancer stem cell-like properties, accompanied by increased YAP1 expression, in liver cancer cells." (PMID 35930163, 2022). "For example, Mst1/2 loss leads to uncontrolled cell proliferation and differentiation in a mouse liver, and Yap1/Taz overexpression, the transcriptional coactivators of the pathway, triggers tissue overgrowth and cancer." (PMID 36551696, 2022). "At this point, we have just started to understand the high potential of inhibiting the Hippo-YAP1 pathway for cancer therapy." (PMID 35689194, 2022). "In this study, we analyzed YAP1 expression in pan-cancer and evaluated its role in prognostic value, immunomodulation, and drug response." (PMID 36479120, 2022). "This is the first in vivo study to confirm that YAP1 activation is correlated with lesion stiffness, using a human cancer sample." (PMID 36291755, 2022). "We subdivided patients into two groups for each cancer type based on YAP1 expression above or below the median level, and analyzed the differences in 50 hallmark gene sets across 33 cancer types." (PMID 36479120, 2022). "We evaluated the expression of two master mechanosensors and transcriptional activators, Yap1 and Taz, which are essential for triggering cancer initiation and growth of most solid tumors." (PMID 35269446, 2022). "Drug sensitivity analysis shows that in contrast to the association of YAP1/EGFR/MAP2K1 with drug resistance, high expressions of mTOR are favorable to cancer chemotherapy." (PMID 35655775, 2022). "The downregulation of YAP1 was more dramatic in the Cancer Luminal Type B. We also analysed the YAP1 expression level and survival." (PMID 35217640, 2022). "Yes-associated protein 1 (YAP1) is involved in the Hippo pathway, which regulates various cancer phenotypes, especially angiogenesis, carcinogenesis, and metastasis." (PMID 35449153, 2022). "In conclusion, YAP1 is aberrantly expressed in various cancer types and regulated by its DNA methylation and post-transcriptional modifications." (PMID 36479120, 2022). "There are several reports which indicates that, YAP1 plays an important role in other types of cancers too." (PMID 34196131, 2022). "The prediction target of microRNA suggested that miR-596-3p was considered to modulate two genes essential in the brain invasion process, YAP1 and IL-8 that restrain the invasion of cancer cells and permeability of BBB, respectively." (PMID 35961957, 2022). "Caution should thus be taken, especially in the context of pharmaceutical interest in developing inhibitors for YAP1 or TAZ for ant-cancer treatment." (PMID 35930163, 2022). "YAP1 was aberrantly expressed in various cancer types and regulated by its DNA methylation and post-transcriptional modifications." (PMID 36479120, 2022). "For example, nuclear translocation and protein stability of YES-associated protein 1 (YAP1) is regulated by O-GlcNAcylation, and elevated YAP1 expression is associated with antiapoptotic effects, migration/invasion, EMT, and cancer stemness in UCB." (PMID 35625898, 2022). "For instance, the EMT transcription factor ZEB1 turned into a transcriptional activator once it started interfering with YAP1 in more aggressive cancers." (PMID 35223831, 2022). "In this study, the YAP1 expression pattern and its prognostic value in patients with cancer were analyzed." (PMID 35685435, 2022). "While loss‐of‐function mutations in core Hippo pathway components occur infrequently in cancer, YAP1 expression is upregulated in a variety of cancers including in RMS." (PMID 36037042, 2022).
cancer (continued). "Compared with adjacent normal tissues, YAP1 expression in cancer was significantly higher in CHOL, COAD, LIHC, STAD." (PMID 35685435, 2022). "Metformin was reported to inhibit the proliferation of some cancer cells via the YAP1 pathway, which is the key factor in the Hippo pathway." (PMID 35264157, 2022). "Cox regression analysis results from 33 types of cancer suggested that YAP1 expression positively correlated with poor OS in patients with PAAD and LGG with significance." (PMID 35685435, 2022). "SCCs of the lung, oesophagus and head and neck display the highest levels of YAP1 or WWTR1 gene amplifications across multiple cancer types, often in a mutually exclusive manner." (PMID 35913427, 2022). "As such, YAP-1 and Vinculin represent a molecular entry point to better understand the high sensitivity of cancer cells to the changes in mechanical properties of the external environment, including mechanical unloaded condition." (PMID 35662260, 2022). "Thereby, AT-101 appears to target cancer stem cells by abrogating YAP1/SOX9/β-catenin signaling in addition to suppress anti-apoptotic signaling even when Bcl-2 is downregulated." (PMID 35215257, 2022). "Together with our results demonstrate the existence of a YAP1-dependent feISC signature that is induced after sublethal CT and favors cancer progression and metastasis." (PMID 35606354, 2022). "We found that YAP1 expression was positively correlated with most immune checkpoint genes and immune cell marker genes in all 33 cancer types." (PMID 36479120, 2022). "Taken together, YY1/DLEU1/miR-149-5p/YAP1 axis exerts crucial cancer-promoting function in CCA progression, and DLEU1 has potentiality as a biomarker or therapeutic target." (PMID 35864972, 2022). "Transcriptional enhanced associated domain (TEAD) transcription factors are the main binding partner for YAP1, and they work together to exert cancer-promoting function." (PMID 35864972, 2022). "YAP (yes-associated protein 1 or YAP1) is a transcription factor for cell proliferation and metastatic dissemination in a variety of cancers." (PMID 35326559, 2022). "Further, it will be interesting to perform in vitro as well as in vivo studies to explore the possible link between YAP1 and IL‐18 for a better understanding of cancer progression." (PMID 34196131, 2022). "Genetic aberrations of Hippo genes and constitutive activation of YAP1 have been described in many different cancer types with varying relevance for cancer progression." (PMID 35689194, 2022). "Activated YAP1 enhances the proliferation, survival, metastasis, and drug resistance of cancer cells." (PMID 36291755, 2022). "Deregulation and consecutive activation of YAP1 is involved in cancer initiation, progression, metastasis, and therapeutic resistance." (PMID 36045416, 2022). "YAP1 not only regulates the proliferation of cancer cells but also plays a central role in mediating resistance to cancer therapy, such as targeted therapies, chemotherapy, immunotherapies and radiotherapy." (PMID 35264157, 2022). "High YAP1 expression was a risk factor for the OS in seven cancer types, PFI in eight cancer types, DFI in six cancer types, and DSS in eight cancer types." (PMID 36479120, 2022). "Both genes are key components of the mammalian EMT/cancer-related Hippo pathway, being YAP1 a major transcriptional regulator and TEAD4 its essential binding partner in gene transcription regulation." (PMID 35500936, 2022). "As a key oncogenic mediator in Hippo signalling, YAP1 is highly expressed in various cancers and maintains cancer growth and invasion activities." (PMID 35264157, 2022). "The Hippo/YAP1 pathway is one of the key oncogenic regulatory pathways in multiple cancers including HNSCC." (PMID 35965328, 2022). "Overexpression of YAP1 induces cancer cells to transform into cancer stem cells, evading cell contact inhibition, thereby enhancing their ability to invade, migrate, and proliferate." (PMID 36532767, 2022).
cancer (continued). "Numerous studies have established YAP1, the key downstream effector of Hippo pathway, as an important oncogene for tumorigenesis, and a promoter of cancer stemness and metastasis." (PMID 35014181, 2022). "In this study, we firstly investigated the expression pattern and prognostic value of YAP1 in pan-cancer analysis using multiple databases and Kaplan-Meier plotter." (PMID 35685435, 2022). "Rescue experiments confirmed that the cancer-promoting effect of DLEU1 was saved by interfering miR-149-5p or YAP1." (PMID 35864972, 2022). "When Hippo signaling is reduced in cancer this leads to the accumulation of YAP1/TAZ complexes in the nucleus in order to promote cell proliferation and survival." (PMID 35956175, 2022). "Only a fraction of cancer cells highly expressed YAP1, implying that only a subpopulation possesses cancer stem cell (CSC)-like characteristics similar to DR MSCs." (PMID 35356283, 2022). "Another mechanism is that YAP1/TEAD directly upregulates CXCL5 in cancer cells to recruit CXCR2-expressing MDSCs, leading to decreased infiltration of CD8+ T cells." (PMID 36479120, 2022). "Numerous studies have confirmed the inhibition of YAP1 by verteporfin in various processes ranging from cancer to wound scarring." (PMID 36276651, 2022). "Through binding at GGAA repeats, CIC regulates YAP1 transcriptional output in both normal and human cancer cells." (PMID 36198276, 2022). "Emerging work indicates that YAP1 is widely activated in human malignancies and is essential for cancer initiation, progression, and drug resistance in most solid tumors." (PMID 36479120, 2022). "In this study, we analyzed YAP1 expression in 33 cancer types to reveal its role in predicating prognosis, modulating TME, and drug response to chemotherapeutic and targeted drugs that were FDA-approved or are in clinical trials." (PMID 36479120, 2022). "miR-630 has different gene targets among them are those associated with cancer phenotype such as BCL2, YAP-1 and Slug." (PMID 35248081, 2022). "Yes-associated protein 1 (YAP1) plays a significant role in malignancies, which can promote malignant phenotypes and drug resistance of cancer cells and facilitate expansion of cancer stem cells (CSCs)." (PMID 35601153, 2022). "Verteporfin was also used for YAP1 inhibition in cancer cell lines to confirm the role of YAP1 in MSC--involved tumorigenicity." (PMID 35356283, 2022). "Copy number and expression analysis revealed strong correlations for a subset of the amplified cancer-related genes, YAP1, BIRC2-3, on 11q22." (PMID 34997070, 2022). "The transcriptional regulator Yes-associated protein 1 (YAP1) is the central component of Hippo signaling, and YAP1 plays an oncogenic role in many cancers." (PMID 35110552, 2022). "In this study, we analyzed the correlation between YAP1 expression and infiltration of various immune cells in 33 cancer types." (PMID 36479120, 2022). "YAP1/TAZ are not only essential for cancer initiation, but they also function as sensors of the mechanical or structural features of the cell microenvironment." (PMID 35956175, 2022). "Further, we tried to collect the statistical power of the pan-cancer technique on large numbers of clinical samples to reveal the relationship between YAP1 and MKI67 using TIMER." (PMID 35685435, 2022). "YAP1 has been reported to affect the activity of B cells, Tregs, macrophages, and myeloid-derived suppressor cells (MDSCs) in several cancer types." (PMID 36479120, 2022). "We found that YAP1 was aberrantly expressed in various cancer types and regulated by its DNA methylation and post-transcriptional modifications, particularly m6A methylation." (PMID 36479120, 2022). "Metformin has been reported to be a YAP1 inhibitor in various cancers that can directly phosphorylate YAP1 and inhibit the translocation of YAP1 from the cytoplasm to the nucleus." (PMID 35264157, 2022).
cancer (continued). "In this study, we assessed the role of YAP1 in prognostic value, immunomodulation, and drug response from a pan-cancer perspective." (PMID 36479120, 2022). "First, univariate Cox regression analysis and survival analysis were used to evaluate the effect of YAP1 on the prognosis of cancer patients." (PMID 35685435, 2022). "In carcinoma cell lines, S100P and YAP1 expression levels were both increased under the same treatment, whereas S100P was apparently up- or downregulated after YAP1 knockdown or overexpression." (PMID 36187124, 2022). "For the Hippo pathway, apart from YAP1 that showed upregulation in carcinoma cell lines (H314, H157, H413 and SqCC/Y1), WWTR1/TAZ was also overexpressed in H314, H413 and SqCC/Y1 plus D17‐TERT dysplasia line." (PMID 35000271, 2022). "The overexpression also caused a decrease in expression of cancer-promoting factors EZH2, DNMT1, FOXM1, EGFR, PCNA, AURKA, YAP1, and CDH2." (PMID 34595169, 2021). "Nuclear-localized YAP1/TAZ binds transcriptional enhanced associate domain (TEAD), and regulates gene transcription related to multiple cancer-associated features." (PMID 33970925, 2021). "In this study, we first evaluated the transcriptional levels of YAP1 and its prognostic values in various types of cancers by the multiplatform (Oncomine, GEPIA, and DriverDBV3)." (PMID 34257617, 2021). "The authors of this study found that YAP1 was upregulated in cancer tissues with stiffer matrices than in normal tissues." (PMID 34577765, 2021). "YAP1 was upregulated in cancers based on 22 significant unique analyses and YAP1 was downregulated in seven unique analyses." (PMID 34257617, 2021). "Meanwhile, qRT-PCR analysis also revealed that YAP1 was up-regulated in spheres compared with adherent cancer cells." (PMID 34715859, 2021). "Using the Kaplan–Meier plotter, GEPIA, and Long-term Outcome and Gene Expression Profiling database of pan-cancers (LOGpc), we further established the prognostic value of YAP1." (PMID 34150844, 2021). "After the nuclear translocation, YAP1 can bind to the enhancer region of PD-L1 and promote transcription activity, which increases the level of PD-L1 in cancer cells." (PMID 34852849, 2021). "In the current study, we conducted a systemic analysis of the expression and the prognostic value of YAP1 in different types of cancer." (PMID 34257617, 2021). "YAP1 acts as a central node in relaying Hippo signaling to transcriptional regulation and cancer promotion." (PMID 34094936, 2021). "More importantly, YAP1 inhibitor attenuates the growth and cancer stemness of EnzaR cells in vitro and in vivo." (PMID 33664454, 2021). "Verteporfin, a known YAP1 inhibitor, has received a great deal of interest as a potential therapeutic modality for various cancers." (PMID 33830081, 2021). "Many different cancer types harbor aberrant YAP1 activation, and examples range from tumors of the lungs, liver, skin and pancreas to tumors of the breasts, uterus, prostate, head and neck cancers and gliomas." (PMID 34685695, 2021). "During cancer development, YAP1 functions as an oncogene by promoting cancer stem cell-like properties." (PMID 35201494, 2021). "Given the prognostic values in ACC, LGG, and PAAD, we screened the common YAP1-coexpressed genes in the three types of cancers, which were annotated by the Metascape and DAVID database, respectively." (PMID 34257617, 2021). "We propose that in the early stages, when cancer cells have a low level of malignancy, YAP1-1 is predominant due to its weaker binding with negative regulatory factors than YAP1-2 and mainly promotes cell proliferation." (PMID 34094936, 2021). "Functional analyses reveal that YAP1 positively regulates numerous genes related to cancer stemness and lipid metabolism and interacts with COUP-TFII to form a transcriptional complex." (PMID 33664454, 2021).
cancer (continued). "YAP1 is a transcriptional activator in the Hippo signaling pathway, and the transcriptional response induced by YAP1 is crucial to the proliferation and metastasis of cancer cells." (PMID 34097315, 2021). "YAP1 has been demonstrated to facilitate the proliferation, invasion and epithelial–mesenchymal transition of various types of cancer cells." (PMID 34462427, 2021). "Our study also demonstrates that miR-509-3p abrogates cancer cell stemness via downregulation of YAP1." (PMID 34715859, 2021). "Transcriptional enhanced associate domain (TEAD) is the main binding partner of Yes-associated protein 1 (YAP1) and acts as a transcriptional activator in various cancers." (PMID 34494089, 2021). "According to the median mRNA levels of YAP1, Kaplan-Meier survival analysis was performed in pan-cancers." (PMID 34257617, 2021). "Our results were in consistent with the previous studies which supported that YAP1 is an oncogene and aggravates drug resistance and cancer cell stemness in NSCLC." (PMID 34715859, 2021). "Overall, GNE-7883 represents an attractive molecule to further probe the Hippo pathway in cancer and the impact of allosteric inhibition of the YAP1–TEAD complex on efficacy across different indications and genetic backgrounds." (PMID 34685695, 2021). "The high levels of COX-2 and HMGB1 promoted inflammation and DNA damage, marked by 8-NitroG and 8-OxodG, and the dedifferentiation of cancer cells into YAP1- and SOX9-positive CSCs in the colonic tissue." (PMID 33807620, 2021). "In the current study, we integrated the public databases to investigate the expression pattern and the prognostic performance of YAP1 across human cancers." (PMID 34257617, 2021). "Analysis of gene expression data using TIMER 2.0 shows a moderate-to-strong correlation between WNT5A and YAP1 in several cancer types." (PMID 33643710, 2021). "ACTL6A has been reported to drive cancer progression by stabilizing the YAP1/TAZ pro-cancer transcriptional regulators, and by suppressing expression of the p21Cip1 cyclin-dependent kinase inhibitor." (PMID 34689163, 2021). "As a consequence, hyperactivation of YAP1 and expression of YAP1 target genes promote cancer initiation, progression and drug resistance." (PMID 34462427, 2021). "Dysregulation of YAP1 affects transcription of various genes related to cell proliferation and migration, subsequently contributing to cancer development." (PMID 33834618, 2021). "By mediating its target gene transcription in most cancer cells, YAP1 plays multiple regulatory roles in cancer progression." (PMID 33834618, 2021). "Inactivation or deregulation of this signaling pathway in cancer leads to translocation of YAP1 and TAZ in the nucleus, where they reprogram cells to acquire stem-like characteristics." (PMID 34205978, 2021). "The importance of Hippo/YAP1 and deregulation of the Hippo pathway during cancer development and progression are emerging." (PMID 33588867, 2021). "Despite the intensive observation, the YAP1-mediated mitochondrial dysfunction in human cancers is still elusive." (PMID 34257617, 2021). "YAP1 is an evolutionary conserved transcription cofactor of the Hippo pathway, which regulates the development of organs and is deregulated in many human cancers." (PMID 33803512, 2021). "Our research strongly suggests that multiple genetic events and aberrant pathway activation result in increased YAP1 activity, resulting in increased cancer cell survival via Hippo/YAP." (PMID 33808166, 2021). "This study aimed to comprehensively understand the prognostic performances of YAP1 expression and its potential mechanism in pan-cancers by mining databases." (PMID 34257617, 2021). "Increasing evidence shows that YAP1 drives oncogenesis in several types of cancer; however, its role in MB remains elusive." (PMID 34944872, 2021). "YAP1 facilitates cancer progression in numerous ways, including promoting cell proliferation, expansion of cancer stem cells, and drug resistance." (PMID 35059315, 2021).